NRP1 (neuropilin 1)
Diseases named in the same sentence as NRP1 in open-access papers (continued):
Sharing a sentence is not in itself a finding about the gene and the disease.
leukemia (14 papers, 2013 to 2025). A malignant (clonal) hematologic disorder, involving hematopoietic stem cells and characterized by the presence of primitive or atypical myeloid or lymphoid cells in the bone marrow and the blood. "NRP-1 has been extensively researched as a prognostic biomarker and therapeutic target in cancer and leukemia." (PMID 38791476, 2024). "In an independent study, SEMA3A was also found to induce apoptosis in leukemia cells, via NRP1 co-receptor." (PMID 31143707, 2019). "Noteworthy, current data support a promoting role for Semaphorin 4D and Neuropilin-1 in these tumors, while Semaphorin 3A seems to consistently act as oncosuppressor in leukemias and multiple myeloma." (PMID 31143707, 2019). "Silencing of the NRP-1 gene results in a significant decrease of VEGF- induced cell proliferation and migration in HEL cells, suggesting the role of VEGF in leukemia progression via its newly identified receptor, NRP-1." (PMID 24385810, 2013). "Interestingly, the introduction of exogenous Sema3A, which serves as a ligand for NRP-1, can effectively downregulate NRP-1 expression on Tregs and facilitate the apoptosis of leukemia cells." (PMID 40771826, 2025). "Moreover, it was demonstrated that a cell-internalized oligopeptidic molecule targeting NRP1 displays potent anti-leukemia cell effect." (PMID 31143707, 2019). "Here, such T cells were capable of overcoming established leukemia in a majority (>75%) of recipient mice regardless of Nrp1 expression." (PMID 25343644, 2014). "Interestingly, it has been shown that NRP1 transcripts are targeted by miR-9 that was found to be downregulated in ALL cells; indeed miR-9 forced re-expression could inhibit leukemia cell proliferation and cell cycle progression." (PMID 31143707, 2019).
liver fibrosis (14 papers, 2017 to 2026). "This approach targets multiple pathogenic mechanisms simultaneously, positioning NRP-1 as a promising therapeutic target for liver fibrosis." (PMID 40419692, 2025). "In conclusion, NRP-1 is a pivotal mediator in the pathogenesis of liver fibrosis, with its expression and function intricately linked to disease progression." (PMID 40419692, 2025). "Since NRP1 has been shown to increase TGFβ‐dependent collagen production in a model of liver fibrosis, we examined the response of Nrp1‐ko myofibroblasts to 24 h TGFβ stimulation." (PMID 41432227, 2026). "Beyond the canonical activation of c-Met by HGF binding, NRP-1 act as a co-receptor, further stimulating c-Met, exacerbating liver fibrosis." (PMID 40419692, 2025). "Hepatocyte NRP-1 expression increased significantly during liver fibrosis and was positively correlated with HGF/c-Met expression and fibrosis severity." (PMID 40419692, 2025). "We investigated the role of hepatocyte-specific NRP-1 deletion in liver fibrosis progression and its relationship with the HGF/c-Met pathway." (PMID 40419692, 2025). "We demonstrated a notable upregulation of NRP-1 expression in hepatocytes, which correlated positively with to c-Met in the context of liver fibrosis." (PMID 40419692, 2025). "Our subsequent investigations revealed that hepatocyte NRP-1 functions as a co-receptor for c-Met during liver fibrosis." (PMID 40419692, 2025). "Hepatocyte-specific NRP-1 knockout mice were generated using the Cre-lox system, and liver fibrosis was induced by carbon tetrachloride injections or a methionine- and choline-deficient diet." (PMID 40419692, 2025). "Our previous studies revealed that NRP-1 contributes to hepatic fibrosis by functioning as a co-receptor for PDGF-B and transforming growth factor-beta (TGF-β) in HSCs." (PMID 40419692, 2025). "Conversely, other studies have shown that NRP1 is upregulated and contributes to the activation of hepatic stellate cells and the development of liver fibrosis." (PMID 38646784, 2024). "In particular, a recent study found that empagliflozin suppresses liver fibrosis by regulating different pathways (Galectin-1/Neuropilin-1) related to LSEC and HSC communication." (PMID 38534382, 2024). "Neuropilin-1 (NRP-1) promotes the abnormal deposition in hepatic fibrosis, and the expression of NRP-1 is significantly elevated in hepatic fibrotic liver tissues." (PMID 39113708, 2024). "To explore how NRP1 was upregulated in liver fibrosis, we transfected Flag-NRP1 in mouse primary HSCs, followed by Co-IP and LC-MS/MS proteomic analysis to examine NRP1-interacting proteins." (PMID 36653359, 2023). "Since HSC activation is the central role of liver fibrosis, NRP1 is a potential therapeutic target for rescuing liver fibrosis." (PMID 36077090, 2022). "A recent report showed that the interaction of galectin-1 with neuropilin-1 promotes liver fibrosis by activating the hepatic stellate cells." (PMID 33431823, 2021). "Hepatocyte growth factor (HGF)/c-Met signaling critically influences liver fibrosis, but its interaction with neuropilin-1 (NRP-1) in hepatocytes remains unclear." (PMID 40419692, 2025). "Given that hepatocytes stimulate the activation of HSCs and HSECs, driving liver fibrosis and cirrhosis progression, elucidating the function of NRP-1 in hepatocytes could potentially impede or reverse fibrosis in its early stages." (PMID 40419692, 2025). "These interventions could be particularly effective in the early stages of liver fibrosis, underscoring the importance of NRP-1 as a therapeutic target for future clinical applications." (PMID 40419692, 2025). "Targeting the HGF/RARA/NRP-1 axis may offer a promising therapeutic strategy for managing liver fibrosis, potentially by developing drugs that modulate NRP-1 expression or function." (PMID 40419692, 2025). "NRP-1 expression was significantly higher in human liver fibrosis than in normal tissues." (PMID 40419692, 2025).
liver fibrosis (continued). "Additionally, the transmembrane receptor Neuropilin-1 (NRP1) has been identified as upregulated in the livers of mice with induced liver fibrosis." (PMID 38816668, 2024). "Inactive USP9X ameliorated liver fibrosis in vivo via destabilizing NRP1." (PMID 36653359, 2023). "Our data thus shed new lights into mechanisms underlying stellate cell activation and liver fibrosis and targeting USP9X/NRP1 might serve as potential target for liver fibrosis." (PMID 36653359, 2023). "Moreover, USP9X expression inhibition attenuated HSC activation and liver fibrosis, accompanied by low NRP1 expression." (PMID 36653359, 2023). "Inactivation of NRP1 prevented Ccl4-induced liver fibrosis in vivo." (PMID 36653359, 2023). "Cell-surface glycans and Gal-1 promote HSC activation and migration; therefore, disrupting glycosylation-dependent Gal-1/neuropilin-1 interactions may be a possible therapy for liver fibrosis." (PMID 32231658, 2020). "Our results not only demonstrated the cooperative effect of Gal-1 and glycosylation changes in HSC activation but also implied that targeting glycosylation-dependent Gal-1/NRP-1 interactions might be effective in liver fibrosis therapy." (PMID 28887481, 2017). "However, the mechanism through which hepatocyte NRP-1 promotes liver fibrosis remains unclear and requires further investigation." (PMID 40419692, 2025). "Targeting NRP-1 in hepatocytes could effectively inhibit or reverse liver fibrosis." (PMID 40419692, 2025). "Indeed, NRP1 has a critical role in liver fibrosis and cirrhosis pathogenesis." (PMID 35978143, 2022). "HGF-induced upregulation of hepatocyte NRP-1, mediated by RARA binding to its promoter, drives liver fibrosis through c-Met pathway activation, highlighting NRP-1 as a potential therapeutic target for liver fibrosis." (PMID 40419692, 2025). "Hepatocyte NRP-1, whose expression is upregulated by HGF by binding the transcription factor RARA to its potential promoter regions, promotes liver fibrosis via the c-Met signaling pathway." (PMID 40419692, 2025). "Thus, targeting NRP1 or USP9X for treating liver fibrosis could bring up new therapeutic options." (PMID 36653359, 2023). "NRP1 deubiquitination mediated by USP9X enhances HSC activation, implying that targeting NRP1 or USP9X potentiates novel options in the treatment of liver fibrosis." (PMID 36653359, 2023). "Therefore, targeting Gal-1/NRP-1 interactions could be developed into liver fibrosis therapy." (PMID 28887481, 2017). "HGF further upregulates NRP-1 through the transcription factor RARA, exacerbating liver fibrosis." (PMID 40419692, 2025). "We aimed to investigate whether the NRP-1 and HGF/c-Met pathways interact to drive liver fibrosis progression." (PMID 40419692, 2025). "In this study, we investigated whether NRP-1 and the HGF/c-Met pathways interact to drive the progression of liver fibrosis." (PMID 40419692, 2025). "In conclusion, NRP1 contributes to HSC activation and liver fibrosis." (PMID 36653359, 2023). "Moreover, USP9X was found to be a critical deubiquitinating enzyme for the stability and high activity of NRP1 and NRP1 deubiquitination mediated by USP9X enhanced HSC activation and liver fibrosis." (PMID 36653359, 2023). "It has been reported that galectin-3 (Gal-3) promotes HSC activation and liver fibrosis but Gal-3 did not interact with NRP-1, suggesting Gal-3 regulates HSC homeostasis through distinct mechanisms compared to Gal-1." (PMID 28887481, 2017). "However, the role of NRP-1 in hepatocytes and its potential interaction with HGF/c-Met in exacerbating liver fibrosis remains unknown." (PMID 40419692, 2025). "Therefore, this study investigated whether the glycome of activated HSCs facilitates Gal-1 binding to NRP-1 to induce HSC activation and migration, and liver fibrosis." (PMID 28887481, 2017).
Alzheimer disease (13 papers, 2017 to 2026). A progressive, neurodegenerative disease characterized by loss of function and death of nerve cells in several areas of the brain leading to loss of cognitive function such as memory and language. "In particular, Nrp1 in the CSF was proposed to be associated with Alzheimer’s disease and aging in humans." (PMID 36399562, 2022). "Patients with Alzheimer’s disease, compared to healthy people, are characterized by significantly higher levels of leptin, cystatin C and tau protein, and lower levels of neuropilin-1." (PMID 37959320, 2023). "Subcluster 2 expressed high levels of white matter associated genes (NRP1, MERTK, and NCKAP5) while subcluster 3 displayed a disease‐associated signature (STARD13, MITF, GPNMB, and DPYD) previously observed in Alzheimer's disease (AD) and Multiple Sclerosis (MS)." (PMID 41283828, 2026). "Neuropilin-1 (NRP1) has been shown to be upregulated in patients with severe Alzheimer’s disease." (PMID 37280551, 2023). "Thus, we hypothesize that NRP1 may be upregulated in Alzheimer’s disease (AD) patients and that a correlation between AD and SARS-CoV-2 NRP1-mediated infectivity may exist as angiotensin converting enzyme 2 (ACE2)." (PMID 34745215, 2021).
neuroblastoma (13 papers, 2006 to 2025). Neuroblastoma (NB) is the most common solid, extracranial childhood tumor. "In neuroblastomas, a higher level of NRP1 expression was associated with a longer survival time." (PMID 34277411, 2021). "Knockdown of NRP1 promotes the migration and invasion of human neuroblastoma SK-N-AS cells through a mechanism involving stimulation of β1 integrin expression." (PMID 37894289, 2023). "Hypoxia has been shown to up-regulate the expression of NRP-1 in certain normal cell types like the monkey choroid-retinal endothelial cells, ES cells and also in neuroblastoma cells." (PMID 23185562, 2012). "We observed that N1E-115 cells express both HIF1α and HIF2α, their common target genes VEGF and adrenomedullin as well as several neuroblastoma classical markers including neuropilin-1, neuronal-specific enolase, Id2 and chromogranin A." (PMID 17655754, 2007). "Overall, our data clearly indicate that RA-differentiated SH-SY5Y neuroblastoma cells show an increased expression of the surface molecules used by SARS-CoV-2 to enter the cells, namely NRP1, TMPRSS2, and, to a lesser extent, ACE2." (PMID 34834998, 2021). "Here, we show that SH-SY5Y neuroblastoma cells express three important cellular surface molecules that interact with the Spike protein, namely ACE2, TMPRSS2, and NRP1." (PMID 34834998, 2021). "A study using tumor biopsies from children with neuroblastomas (NBs) to assess the mRNA expression of neuropilin with quantitative RT-PCR showed that NRP1 and NRP2 mRNA and protein levels are higher in stages I-IV NB compared to non-tumor controls." (PMID 37894289, 2023).
renal cell carcinoma (13 papers, 2014 to 2025). "A previous study also found that NRP1 expression was related with improved survival in renal cell carcinoma." (PMID 36338984, 2022). "Similarly, the receptors VEGFR2 (KDR) and NRP1 were decreased or relatively unchanged in prostate primary tumors while they were up-regulated in renal cell carcinoma (d for prostate, h for kidney)." (PMID 26341082, 2015). "Finally, numerous studies have described the expression of NRP1 on tumour cells, which can modify EC behaviour and alter their angiogenic potential, with an impact on tumour cell proliferation in human pancreatic and renal cell cancer." (PMID 39668325, 2024). "In addition, it will be important to determine what role additional VEGF receptors may play in the intracrine signalling pathway, such as NRP1 which likely mediates the intracrine VEGF function in renal cell carcinoma." (PMID 33478167, 2021). "Studies have previously reported NRP1 to complex with ITGA5 in HUVECs and NRP2 to complex with ITGA5 from co-cultures between HUVECs and renal cell carcinoma." (PMID 32528960, 2020). "A non-angiogenic role for VEGF in renal cell carcinoma has also been discovered, whereby autocrine VEGF promotes cell growth through interaction with Nrp1." (PMID 33478167, 2021).
breast tumor (12 papers, 2010 to 2022). "In order to determine the association between plasma NRP-1 and PlGF and their corresponding expression in the tumor tissue, immunohistochemical staining was carried out on breast tumor tissue representative of the nodal and metastatic status subgroups." (PMID 28607365, 2017). "We further compared FOXO3a, VEGF-A, and NRP1 expression in a tissue microarray containing 100 independent primary breast tumor samples by immunohistochemistry." (PMID 33262463, 2021). "This study lacks the possibility to analyze corresponding tissue expression of NRP-1 in the breast tumors." (PMID 33884469, 2021). "The role of Neuropilin-1 (NRP-1) and its interacting molecules in breast tumor tissue was correlated with cancer progression; however, the clinical impact of their systemic levels was not extensively evaluated." (PMID 28607365, 2017). "The expression of NRP-1 in the breast tumor tissue displays a similar pattern to its plasma counterpart." (PMID 28607365, 2017). "GPNMB increases the expression of neuropilin-1 (NRP-1) that forms a complex with VEGFR2 to enhance tumor cell-intrinsic VEGF signaling and primary breast tumor growth." (PMID 27304911, 2016). "For example, studies in a wide range of breast tumors have shown that NRP1 and NRP2 are both expressed on almost all endothelial cells, but very rarely on breast tumor cells." (PMID 23667446, 2013). "Nrp1 can also be expressed by tumor cells themselves, and a peptide which inhibits VEGF-Nrp1 interactions has been shown to induce apoptosis of Nrp1-expressing breast tumor cells." (PMID 31118303, 2019). "Recently, our studies have found that breast tumor cells are capable of modulating the migration of vascular SMCs in vitro, and this event is mediated through vascular endothelial growth factor (VEGF)/B-form of platelet-derivative growth factor (PDGF-B) - neuropilin-1 (NRP-1) signaling pathways." (PMID 20687910, 2010).
lymph node metastasis (12 papers, 2014 to 2023). "Further clinically relevant analysis showed that elevated HIF-1α and NRP1 expression was associated with lymph node metastasis." (PMID 33850110, 2021). "In cancer cells, NRP1 overexpression was associated with poor prognosis and lymph node metastasis." (PMID 35347234, 2022). "Our results indicate that NRP1 may regulate the EMT process in OSCC cell lines through NF-κB activation, and that higher NRP1 expression levels are associated with lymph node metastasis and poor prognosis in OSCC patients." (PMID 24999732, 2014). "In epithelial ovarian carcinoma, NRP1 levels are higher in tumors at an advanced stage and present lymph node metastasis and distant metastasis, and higher NRP1 expression strongly predicts shorter survival." (PMID 37894289, 2023). "Along these lines, when patients with NSCLC were classified into low and high NRP1 expression groups, a strong correlation was identified between histological grade, TNM stages and lymph node metastasis with high NRP1 levels." (PMID 35884516, 2022). "Lower levels of FOXO3a and higher levels of VEGF-A or NRP1 were correlated with shorter survival in the lymph node metastasis positive subgroup." (PMID 33262463, 2021). "By using the same analyses based on expression levels of NRP-1 mRNA and miR-320a, we found that both were correlated with tumor differentiation, lymph node metastasis, and portal vein invasion." (PMID 32801339, 2020). "Moreover, high expression of NRP1 was significantly correlated to lymph node metastasis and poor prognosis in OSCC patients." (PMID 24999732, 2014). "Moreover, we found that high levels of VEGF-A and NRP1 were correlated with lymph node metastasis." (PMID 33262463, 2021). "NRP1 expression rate in patients without lymph node metastasis was much lower than those with lymph node metastasis (OR = 0.667, 95%CI = 0.522 − 0.854, P = 0.001)." (PMID 33014187, 2020). "Moreover, NRP1 expression gradually increased with the increase in Gleason score, and NRP1 expression was significantly higher in PCa patients with lymph node metastasis when compared with those without lymph node metastasis (P = 2.76e-03)." (PMID 36841806, 2023). "Similar to our findings, that study observed a significant correlation between high NRP1 levels and III-IV stages of tumor-node-metastasis (TNM) classification, poor differentiation and lymph node metastasis, with an absence of association with tumor size greater than 5 cm." (PMID 35884516, 2022).